Y_RNA (Y RNA )
Gene: Miscellaneous RNA gene on chromosome 14 (73,906,316 to 73,906,427, reverse strand). Ensembl gene ENSG00000199472.
Homologues: Orthologues: chimpanzee Y_RNA (98% identical), macaque Y_RNA (91% identical). Paralogues in human: Y_RNA (88% identical), RNY1 (86% identical), Y_RNA (86% identical), Y_RNA (85% identical), RNY1P7 (84% identical), Y_RNA (84% identical), RNY1P11 (83% identical), RNY1P8 (83% identical), Y_RNA (83% identical), Y_RNA (82% identical), Y_RNA (81% identical), Y_RNA (80% identical), and 95 more.